FSHR (follicle stimulating hormone receptor)
Diseases named in the same sentence as FSHR in open-access papers (continued):
Sharing a sentence is not in itself a finding about the gene and the disease.
Insulin resistance (4 papers, 2017 to 2025). Increased resistance towards insulin, that is, diminished effectiveness of insulin in reducing blood glucose levels. "Previous studies have been conducted on many candidate genes for PCOS, principally related to reproductive hormones, insulin resistance, and chronic inflammation, including follicle-stimulating hormone receptor (FSHR), insulin receptor (INSR), and tumor necrosis factor (TNF)." (PMID 29232372, 2017).
kidney cancer (4 papers, 2013 to 2023). Primary or metastatic malignant neoplasm involving the kidney. "Concerning the validation of tumor-related FSHR expression, the present data indicated that only a minority of tissue samples derived from patients suffering from ovarian, prostate or kidney cancer showed FSHR-positive staining in tumor cells." (PMID 31548530, 2017). "In the case of kidney cancer, 29/31 samples (93.5%) showed positive staining for FSHR in small vessels, and in 3/31 (10%) samples, a positive FSHR signal was detected in cancer cells (1 weak IS, 1 moderate IS, and 1 strong IS)." (PMID 31548530, 2017).
Ovarian cyst (4 papers, 2009 to 2023). The presence of one or more cysts of the ovary. "Mutations of the LHCGR and FSHR genes may result in the development of ovarian cysts or hyperfunction, however in this study we did not identify mutations in either of these genes." (PMID 20593028, 2010).
Primary amenorrhea (4 papers, 2020 to 2023). "It is well-established that mutations in the FSHR are rare, and only 25 loss-of-function mutations in FSHR have been found in women with ovarian dysgenesis, primary amenorrhea, and secondary amenorrhea." (PMID 36341241, 2022). "Patients with partially inactivating FSHR variants have displayed a range of clinical manifestations such as primary amenorrhea, secondary amenorrhea, and oligomenorrhea, which is in contrast to completely inactivating FSHR variants that cause fully absence of sexual development." (PMID 36704038, 2022). "Inactivating mutations of follicle-stimulating hormone receptor (FSHR) previously reported in women with ovarian dysgenesis, primary amenorrhea, and secondary amenorrhea." (PMID 36341241, 2022). "Numerous evidence indicates that the clinical manifestations of FSHR variants are not uniform, ranging from primary amenorrhea with puberty disorders to secondary amenorrhea, oligomenorrhea, and premature menopause, depending on the specific domain and type of variant and the degree of inactivation." (PMID 36704038, 2022). "In this study, one novel heterozygous frameshift deletion (c.507delC:p.Phe170Leufs*4) and one reported heterozygous missense (c.1298C>A:p.Ala433Asp) in the FSHR were identified in POI-38, a 23-year-old girl presenting with primary amenorrhea and delayed puberty." (PMID 33095795, 2020).
Thyroid adenoma (4 papers, 2015 to 2023). The presence of a adenoma of the thyroid gland. "Some involved genes include the follicle-stimulating hormone receptor (FSHR), the luteinizing hormone receptor (LHR), INSR, thyroid adenoma-associated (THADA), ERB, and high mobility group A2 (HMGA2)." (PMID 37881324, 2023).
thyroid cancer (4 papers, 2015 to 2023). "In contrast, the FSHR expression can be detected in tumoral cells of majority (88.8%, 32/36) of thyroid cancers." (PMID 25685198, 2015). "A tendency towards the higher frequency of FSHR – positive blood vessels also concerns malignant thyroid tumours." (PMID 25685198, 2015). "The observations presented above confirm that, like in the other human neoplasms, thyroid cancers in the great majority express FSHR in contrast to the non-neoplastic thyroid epithelium." (PMID 25685198, 2015).
atherosclerosis (3 papers, 2023 to 2025). A disease characterized by the build-up of fatty material and calcium deposition in the arterial wall resulting in partial or complete occlusion of the arterial lumen. "However, it remains unknown whether the FSH-receptor (FSHR) is expressed in human atherosclerosis plaques." (PMID 38702476, 2024). "Studies in mice also found that FSH could promote lipid synthesis and lipid drome formation in visceral fat through the Gαi/Ca2+/CREB pathway, and activate endothelial VACM‐1through the FSHR/Gas/cAMP/PKA and PI3K/Akt/mTOR/NF‐kB signaling pathways to promote atherosclerosis." (PMID 37221966, 2023).
Cognitive impairment (3 papers, 2022 to 2024). Abnormal cognition is characterized by deficits in thinking, reasoning, or remembering. "Mechanistically, FSH, FSH receptor (FSHR), G protein coupling, gene mutation and other pathways are involved in adipogenesis and cognitive impairment." (PMID 36545281, 2022). "In mice, we previously showed that follicle–stimulating hormone (FSH), a gonadotropin that rises in post–menopausal females, activates its receptor FSHR in the hippocampus, to drive AD–like pathology and cognitive impairment." (PMID 37852961, 2023). "FSHR gene modification may be a potential strategy to prevent and treat cognitive impairment during menopause." (PMID 36545281, 2022).
cyst (3 papers, 2019 to 2023). A sac-like closed membranous structure that may be empty or contain fluid or amorphous material. "Abundance of mRNA encoding PGRb, AR and STAR was significantly increased in GCs from cysts compared to control GCs, and mRNA levels for both LHCGR and FSHR were significantly lower in cyst CGs in comparison to controls (p < 0.05)." (PMID 37760251, 2023). "Indeed, mRNA levels for both LHCGR and FSHR were significantly lower in our cyst group samples in comparison to controls." (PMID 37760251, 2023).
depression (3 papers, 2022 to 2024). "Therefore, our model illustrates that FSH can contribute to depression by binding to FSHR in the hippocampus." (PMID 39498265, 2024). "Moreover, FSHR knockout mice showed significant depression and affective disorders." (PMID 37679787, 2023). "Overall, our behavioral experiments demonstrated that FSH induced depression and anxiety phenotype in mice, and the behavioral tests on mice treated with FSH and FSHR knockdowns further confirm this conclusion." (PMID 39498265, 2024). "However, our findings do not align with the previous studies by Zhao He, who found that the FSHR ablation induced depressive behaviors, suggesting that FSH signaling is negatively correlated with depression." (PMID 39498265, 2024).
endometrial cancer (3 papers, 2021 to 2025). Primary or metastatic malignant neoplasm involving the endometrium (mucous membrane that lines the endometrial cavity). "As FSH/FSHR has been implicated in distinct hormone-dependent cancers, including endometrial cancer, analysis of the cancer genome database from 575 human endometrial adenocarcinoma tumors revealed that a subpopulation of samples expressed FSHR." (PMID 35185785, 2021).
neuroendocrine tumors (3 papers, 2015 to 2023). "The expression pattern of FSHR in the different layers of the neuroendocrine tumors revealed statistically significant differences between men and women." (PMID 37568488, 2023). "In neuroendocrine tumours, the FSHR-positive blood vessels are more often present in the samples with higher proliferation index." (PMID 25685198, 2015). "The same area of appendix tissue from different immunostaining slides was selected to show the co-expression of CD31 (A, a, a’) and FSHR (B, b, b’) in endothelial cells of capillaries growing in neuroendocrine tumors (green arrows) and into peritumoral (red arrows) areas." (PMID 37568488, 2023). "In our research, FSHR was evaluated in the appendix in the plasma membranes of tumor cells in patients with neuroendocrine neoplasms, and we observed negative signals from normal control tissues." (PMID 37568488, 2023). "The percentages of FSHR-positive cells with weak, moderate, or strong expression in neuroendocrine tumors showed no statistical differences between the layers of the appendix." (PMID 37568488, 2023).
ovarian diseases (3 papers, 2017 to 2026). "The genes KISS1 and FSHR were related to ovarian diseases like POF and PCOS43,44." (PMID 31745224, 2019). "As a measure of accuracy, we inspected the results of the statistical analysis of two genes that are well documented as highly related to ovarian diseases: the gene FSHR, which is a follicle stimulating-hormone, and the gene LHCGR, which is a luteinizing/choriogonadotropin receptor hormone." (PMID 28825658, 2017). "From these genes, FSHR and LHCGR were selected for further analysis because it is known they are highly related to ovarian diseases." (PMID 28825658, 2017).
postmenopausal osteoporosis (3 papers, 2015 to 2026). Metabolic disorder associated with fractures of the femoral neck, vertebrae, and distal forearm. "Elevated FSH has been detected in postmenopausal women, suggesting it negatively impacts BMD and it was proposed that FSH contributes to postmenopausal osteoporosis by stimulating osteoclast differentiation through the FSH receptor (FSHR) expressed on osteoclast precursors and mature osteoclasts." (PMID 41496612, 2026). "Recently, follicle stimulating hormone (FSH) through interaction with its receptor (FSHR) has been proposed to play a role in postmenopausal osteoporosis and cardiovascular disease, rather than the loss of estrogen." (PMID 36875462, 2023). "Interestingly, FSHR is expressed in osteoclasts and involved in postmenopausal osteoporosis via FSHR activation coupled to the Gαi subunit; this result provided the first evidence of FSHR expression and physiological function in organs other than the gonads in an age-related process." (PMID 25754247, 2015). "However, further studies have detected FSHR in osteoclasts, suggesting a possible role of FSH in postmenopausal osteoporosis." (PMID 25754247, 2015).
Premature ovarian insufficiency (3 papers, 2019 to 2023). Amenorrhea due to loss of ovarian function before the age of 40. "Folliculogenesis failure caused by the mutation of the FSHR gene led to premature ovarian insufficiency in women." (PMID 37235159, 2023). "Whether follicle-stimulating hormone receptor (FSHR) polymorphisms are implicated in premature ovarian insufficiency (POI) remains controversial." (PMID 31629411, 2019). "In addition, the SNP FSHR rs6166 is a genetic indicator of premature ovarian insufficiency (POI) in Asian women." (PMID 37235159, 2023).
renal carcinoma (3 papers, 2017 to 2024). A carcinoma arising from the epithelium of the renal parenchyma or the renal pelvis. "The focus of this study was to evaluate FSHR as a therapeutic target for ovarian, prostate, and renal cancer." (PMID 31548530, 2017). "Instead, our data confirm the localization of FSHR in endothelial cells at the periphery of ovarian, prostate, and renal cancer." (PMID 31548530, 2017). "Moreover, research has reported that FSHR is present in metastases to lymph nodes, brain, bones, and liver, which were originated from breast, lung, prostate, and renal cancers." (PMID 38505602, 2024). "Indeed, our results suggest that, in accordance to previously published data, FSHR is not a suitable target for monoclonal antibody therapy with direct targeting of ovarian, prostate, or renal cancer cells." (PMID 31548530, 2017).
renal cell carcinoma (3 papers, 2020 to 2025). "In conclusion, our study suggests that molecular ultrasound imaging targeting FSHR or VEGFR-1 markers has real potential to follow-up patients with Renal Cell Carcinoma undergoing tyrosine kinase inhibitor treatment such as sunitinib." (PMID 32355171, 2020).
testicular disorder (3 papers, 2019 to 2024). A non-neoplastic or neoplastic disorder affecting the testis. "Sex hormone receptors, such as AR, LHR, and FSHR, play significant roles in maintaining male sexual function, and their altered expression may be involved in aging-related testicular disorders." (PMID 31018574, 2019).
adenoma (2 papers, 2021 to 2024). A neoplasm arising from the epithelium. "This is further suggested by other human models, such as pituitary FSH-secreting adenomas, and activating FSHR mutations." (PMID 38372906, 2024). "In the current study, we looked at FSHR transcript expression from RNA sequencing of 575 primary endometrial adenocarcinoma and adenoma subtype tumors." (PMID 35185785, 2021). "Given our findings in the endometrial adenocarcinoma cell line, we assessed the levels of FSHR, Gαi/o family members and the β-arrestins from transcriptomic data gathered from RNA sequencing of 575 endometrial adenocarcinoma or adenoma tumors." (PMID 35185785, 2021).
adenomyosis (2 papers, 2022 to 2024). The growth of endometrial tissue inside the muscular wall of the uterine corpus. "The reduced expression of critical oocyte-derived factors, including Foxl2, BMP15, and FSHR, further indicates ovarian dysfunction in adenomyosis." (PMID 38451875, 2024). "The protein levels of all these factors were lower in adenomyosis mice compared with control (FOXL2, P = 0.0499; FSHR, P = 0.0044; BMP15, P = 0.0207)." (PMID 38451875, 2024). "To further investigate how folliculogenesis was impaired in mice affected by adenomyosis, we performed western blot analysis to evaluate the expression of three crucial oocyte-derived factors involved in follicular development: BMP15, FOXL2, and FSHR." (PMID 38451875, 2024). "Adenomyosis has also been found in the uterine horns of some transgenic mice, such as Dicer inactivated mutant mice, follicular stimulating hormone (FSH) receptor (FSHR)-haplo-insufficient mice, Foxl2 deleted mice, and mice with impaired prostaglandin D2 (PGD2) synthesis." (PMID 35330066, 2022).
adrenocortical carcinoma (2 papers, 2019 to 2023). "We analyzed the expressions of receptors of gonadotropin-releasing hormone (GNRHR), luteinizing hormone/chorionic gonadotropin (LHCGR) and follicle-stimulating hormone (FSHR) in human adrenocortical carcinomas and assessed their response to GnRH antagonist therapy." (PMID 30400009, 2019). "In situ hybridization and qPCR analysis of human adrenocortical carcinomas (n = 11–13) showed expression of GNRHR in 54/73%, LHCGR in 77/100% and FSHR in 0%, respectively." (PMID 30400009, 2019).
anovulation (2 papers, 2014 to 2015). The absence of ovulation. "The slight increase in gonadotropin levels was probably not clinically significant under normal physiological conditions, as the distribution of FSHR polymorphisms was not different among fertile controls with regular cycles and those with chronic anovulation." (PMID 25179311, 2014).
autoimmune disease (2 papers, 2016 to 2023). A disorder resulting from loss of function or tissue destruction of an organ or multiple organs, arising from humoral or cellular immune responses of the individual to their own tissue constituents. "Similarly, our case showed no history of autoimmune diseases, normal karyotype, no deleterious mutations in FSHR gene, and some negative autoantibodies." (PMID 27599836, 2016).
autoimmune thyroid disease (2 papers, 2019 to 2025). Inflammatory disease of the thyroid gland due to autoimmune responses leading to lymphocytic infiltration of the gland. "A complex interplay between female reproductive system and thyroid autoimmunity is further reinforced by involvement of two suggestively associated loci (FSHR and ANKR7) in the same gene ontology categories (sex-differentiation and reproductive traits)." (PMID 30926877, 2019). "A body of evidence suggests the role of FSHR genetic variants with thyroid autoimmunity and repetitively suggests a link with many other phenotypes that are characterized by increased thyroid antibodies levels." (PMID 30926877, 2019).
breast tumors (2 papers, 2015 to 2021). "In agreement with previous studies, our present results indicate the presence of specific endothelial cell receptors for FSH at the periphery of breast tumors and add new data on FSHR expression in blood vessels associated with the invasive cancer cell strands." (PMID 25652007, 2015).
female infertility (2 papers, 2016 to 2025). Diminished or absent ability of a female to achieve conception. "Follicle-stimulating hormone receptor (FSHR) and its intracellular signaling control mammalian follicular development and female infertility." (PMID 27882941, 2016). "The knockout of FSH or FSHR in zebrafish leads to female infertility, hindering sexual maturation." (PMID 39851506, 2025).
Hepatic steatosis (2 papers, 2023). Steatosis is a term used to denote lipid accumulation within hepatocytes. "FSH could potentially inhibit the adipogenesis signaling pathway and prevent hepatic steatosis by binding to FSHR on liver cells and downregulating the classic cAMP/PKA/CREB pathway or CREB pathway." (PMID 37550673, 2023). "Finally, disrupting FSHR signaling in the pituitary increases corticosterone levels and induces hepatic steatosis." (PMID 36841874, 2023).
pancreatic neuroendocrine tumor (2 papers, 2021 to 2023). Pancreatic endocrine tumor, also known as pancreatic neuroendocrine tumor (PNET), describes a group of endocrine tumors originating in the pancreas that are usually indolent and benign, but may have the potential to be malignant. "FSHR is reported to be aberrantly expressed in the endothelial cells of tumors affecting various organs including prostate, breast, colon, pancreas, urinary bladder, kidney, lung, liver, stomach, testis, and ovary and pancreatic neuroendocrine tumors." (PMID 34717708, 2021). "For pancreatic neuroendocrine tumors, co-expression of FSHR and chromogranin was observed in tumor cells, with no expression of FSHR on the endothelium labeled with von Willebrandt factor." (PMID 37568488, 2023). "The intensity of FSHR expression did not correlate with histological features of the pancreatic neuroendocrine tumors." (PMID 37568488, 2023).
renal fibrosis (2 papers, 2019 to 2022). A final common manifestation of a wide variety of chronic kidney diseases characterized by glomerulosclerosis and tubulointerstitial fibrosis. "FSHR knockdown significantly reduced FSH‐stimulated transcription and protein levels of PAI‐1 and fibronectin, suggesting that FSH‐mediated renal fibrosis is dependent on functional FSHR." (PMID 31243899, 2019).
soft tissue sarcoma (2 papers, 2021 to 2025). A malignant neoplasm arising from muscle tissue, adipose tissue, blood vessels, fibrous tissue, or other supportive tissues excluding the bones. "Since FSHR is a common marker of tumor vessels, this strategy should in principle be applicable to a wide range of solid tumor types and of soft tissue sarcomas." (PMID 33920299, 2021).
type 2 diabetes (2 papers, 2018 to 2025). "Gene association studies have so far identified 16 candidate loci involved in PCOS, including genes involved in gonadotropin action (LHCGR and FSHR), metabolism and sexual development (ESR1), insulin signaling and type 2 diabetes (INSR, THADA, HMGA2) or cell proliferation (YAP1 and SUMO1P1)." (PMID 40551954, 2025).
vascular malformation (2 papers, 2021 to 2023). A non-neoplastic disorder that is the result of defects of vascular morphogenesis. "Several studies have demonstrated that specific hormone receptors (HR) such as progesterone receptor (PGR), growth hormone receptor (GHR), and follicle-stimulating hormone receptor (FSHR) were present in vascular tumors and vascular malformations." (PMID 37864259, 2023). "FSHR expression was increased in AVM compared to other types of vascular malformations (p<0.0001)." (PMID 34541367, 2021). "In these studies, expression of GHR, FSHR, and PGR was reported mostly in endothelium of vascular malformations." (PMID 37864259, 2023).
acne (1 paper, 2021). An inflammatory process of the sebaceous glands which is characterized by comedones, nodules, papules and/or pustules on the skin. "Similarly, although statistical significance was not achieved (p = 0.084), FSHR rs6166 minor allele carriers tended towards more severe acne (higher GAGS score) compared with homozygous major allele carriers." (PMID 34943568, 2021).